CCDC106 (coiled-coil domain containing 106)
Synonyms: HSU79303; ZNF581
Tractability: PROTAC: ubiquitination databases record sites on it.
Gene: Protein-coding gene on chromosome 19 (55,641,062 to 55,653,161, forward strand). Ensembl gene ENSG00000173581.
Subcellular location: Nucleus
Subcellular location (Human Protein Atlas): Nucleoplasm; Cytosol
Gene Ontology:
Molecular function: protein binding
Cellular component: nucleoplasm; nucleus
Genetic constraint (gnomAD): Loss-of-function variants: 17 observed, 24.52 expected, observed/expected ratio (o/e) 0.69, 90% interval 0.47 to 1.04. The synonymous counts are far from expectation, so gnomAD's model fits this gene poorly and the ratio says little. Missense variants: 337 observed, 399.56 expected, observed/expected ratio (o/e) 0.84, 90% interval 0.77 to 0.92. Synonymous variants: 211 observed, 168.5 expected, observed/expected ratio (o/e) 1.25, 90% interval 1.12 to 1.4.
Homologues: Orthologues: chimpanzee CCDC106 (99% identical), macaque CCDC106 (98% identical), guinea pig CCDC106 (92% identical), pig CCDC106 (90% identical), mouse Ccdc106 (90% identical), dog CCDC106 (78% identical), tropical clawed frog ccdc106 (67% identical), zebrafish ccdc106a (54% identical), zebrafish ccdc106b (49% identical).
Diseases named in the same sentence as CCDC106 in open-access papers:
CCDC106 is named in the same sentence as 16 diseases in open-access papers, as found by Europe PMC text mining. Sharing a sentence is not in itself a finding about the gene and the disease. The quoted sentences say what the papers report.
cervical cancer (4 papers, 2019 to 2024). A primary or metastatic malignant neoplasm involving the cervix. "It was reported that HPV-CCDC106 integration splits a local TAD into two smaller TADs, accompanied by an enhancer hijacking event to form a novel loop structure to increase CCDC106 expression in cervical cancer." (PMID 37055796, 2023). "It would also certainly be worth investigating CCDC106 expression in clinical samples of breast and cervical cancers to determine its clinicopathologic significance." (PMID 30885251, 2019). "Knockdown of CCDC106 or inhibition of CCDC106 phosphorylation suppresses the progression of breast and cervical cancers." (PMID 30885251, 2019). "Moreover, we showed that the inhibition of CCDC106 sensitizes breast and cervical cancer cells to CX-4945." (PMID 30885251, 2019).
breast carcinoma (3 papers, 2017 to 2022). "Subsequent studies demonstrated that CCDC106 can promote proliferation and invasion in non-small cell lung cancer cells and in breast cancer cells." (PMID 35484984, 2022).
non-small cell lung carcinoma (3 papers, 2017 to 2023). A group of at least three distinct histological types of lung cancer, including non-small cell squamous cell carcinoma, adenocarcinoma, and large cell carcinoma. "Our studies revealed that CCDC106 is associated with non-small cell lung cancer progression and unfavorable prognosis." (PMID 28460455, 2017). "The present study demonstrated that CCDC106 expression correlates with advanced TNM stage (P = 0.008), positive regional lymph node metastasis (P < 0.001), and poor overall survival (P < 0.001) in 183 non-small cell lung cancer cases." (PMID 28460455, 2017).
lung carcinoma (2 papers, 2017 to 2019). "In this study, we explored CCDC106 expression patterns and subcellular distributions in both lung cancer tissues and cell lines." (PMID 28460455, 2017). "We overexpressed or silenced CCDC106 to investigate its influence on lung cancer cell cycle regulators, including Cyclins A2, B1, D1, D2, D3, E1, E2, and H. Cyclin A2 and Cyclin B1 protein levels increased following CCDC106 overexpression, and decreased following CCDC106 knockdown." (PMID 28460455, 2017). "CCDC106 facilitated AKT phosphorylation, leading to Cyclin A2 and Cyclin B2 upregulation, and ultimately enhanced proliferation of lung cancer cells." (PMID 28460455, 2017). "We found that CCDC106 was highly expressed in the cytoplasm of NSCLC tumor cells and lung cancer cell lines." (PMID 28460455, 2017). "In conclusion, we demonstrated that CCDC106 is highly expressed and primarily localized in the cytoplasm in NSCLC tissues and lung cancer cell lines." (PMID 28460455, 2017).
lymph node metastasis (2 papers, 2017 to 2022). "CCDC106 cytosolic localization was correlated with advanced TNM stage, lymph node metastasis, and unfavorable prognosis in NSCLC." (PMID 28460455, 2017). "Cytosolic CCDC106 overexpression correlated with advanced TNM stage, positive lymph node metastasis, and unfavorable prognosis, but not with patient age, sex, tumor differentiation, or histopathological type." (PMID 28460455, 2017).
ovarian carcinoma (2 papers, 2022 to 2023). A malignant neoplasm originating from the surface ovarian epithelium. "CCDC106 overexpression and knockdown experiments were employed to examine the role of CCDC106 in the proliferation of ovarian cancer cells." (PMID 35484984, 2022). "A significant association between poor overall survival and high CCDC106 and ATF4 expression levels was observed in human ovarian cancer samples." (PMID 35484984, 2022). "In addition, the overall survival of ovarian cancer patients with high levels of CCDC106 and ATF4 was significantly lower than patients with low levels of CCDC106 (p = 0.0088) and ATF4 (p = 0.0045)." (PMID 35484984, 2022). "Our findings support the notion that CCDC106 can regulate the progression of ovarian cancers." (PMID 35484984, 2022). "Moreover, we found that benign ovarian tumors express little to no CCDC106, but the expression of CCDC106 gradually increased in borderline and malignant ovarian tumors." (PMID 35484984, 2022).
cancer (6 papers, 2019 to 2024). A tumor composed of atypical neoplastic, often pleomorphic cells that invade other tissues. "Thus, our data suggest that the overexpression of CCDC106 is associated with tumorigenesis and cancer progression." (PMID 35484984, 2022). "The different effects of CCDC106 in different cancer cells may result from its different subcellular localization." (PMID 30885251, 2019). "However, the roles of CCDC106 in other cancer types and its upstream regulators have not been investigated." (PMID 30885251, 2019). "However, the roles and upstream regulators of CCDC106 have not been investigated in other cancer types." (PMID 30885251, 2019).
tumor (6 papers, 2017 to 2024). "CCDC106 overexpression promoted A549 cell proliferation and xenograft tumor growth in nude mice, while siRNA-mediated CCDC106 knockdown inhibited H1299 cell proliferation." (PMID 28460455, 2017). "Little is known about the mechanism that regulates CCDC106-induced tumor progression." (PMID 35484984, 2022). "These different CCDC106 subcellular localizations may result from different cell types or tumor origins." (PMID 28460455, 2017). "CCDC106 is a newly discovered protein, whose expression patterns and role in tumor progression were previously unknown." (PMID 28460455, 2017).
CCDC106 also shares sentences with these, for which no sentence is quoted: adenocarcinoma (1 paper); benign ovarian tumors (1); colorectal cancer (1); gastric cancer (1); lung adenocarcinoma (1); melanoma (1); nasopharyngeal carcinoma (1); squamous cell carcinoma (1).